NEDD4L (NEDD4 like E3 ubiquitin protein ligase)
Diseases named in the same sentence as NEDD4L in open-access papers (continued):
Sharing a sentence is not in itself a finding about the gene and the disease.
tumor (continued). "Our findings reveal a novel insight that IR-induced ferroptosis was via two-way regulation of ESR1/NEDD4L to SLC7A11, and ESR1 might be a critical factor responsible for conferring the resistance to radiotherapy and tumor malignancy." (PMID 35252218, 2021). "Collectively, SGK1 expression was upregulated by the PI3K pathway activated by ligation of Dex and GR, and then SGK1 phosphorylated Nedd4l, which led to Smad2 release from the suppressive Nedd4l-Smad2 complex, and subsequent upregulation of CTGF, which finally promoted tumor metastasis." (PMID 34272474, 2021). "The correlation between NEDD4L gene expression and stromal cell infiltration levels or immune cell infiltration level in various types of tumor tissues has not yet been reported." (PMID 34539897, 2021). "Taken together, the results of in vitro cell culture and in vivo xenograft models consistently showed that NEDD4L-mediating UBE2T degradation could inhibit the progression of LUAD cells, and ultimately reduced tumor formation." (PMID 34838005, 2021). "We evaluated the expression levels of CPNE1 and NEDD4L in lung tissues (tumor specimens and adjacent non-tumor specimens) by Western blotting." (PMID 34743202, 2021). "Some genes in this module were connected by processes proposed to be involved in tumor progression, such as DOC2A, CGN (Cingulin), PARD6B, NEDD4L, and SYT9 which belonged to the KEGG pathway, tight junction (TJ) (hsa04530), and GEO term, cell junctions (GO:0030054)." (PMID 32605588, 2020). "Given the correlation between NEDD4L and HIF-1α, we hypothesized that they may be jointly involved in tumor development and progression." (PMID 31673244, 2019). "However, a study showed that NEDD4L suppressed cell growth by phosphorylating ERK1/2 and inducing apoptosis, suggesting that it might play a tumor-suppressive role in HCC by triggering MAPK/ERK-mediated apoptosis." (PMID 36293239, 2022). "Unlike NEDD4, NEDD4L exhibits more complex roles in tumor progression." (PMID 35646490, 2022). "Ligation of Dex and glucocorticoid receptor (GR) on tumor cells activated the PI3K signaling pathway and upregulated serum glucocorticoid-inducible kinase 1 (SGK1) expression, and then increased the expression of connective tissue growth factor (CTGF) through Nedd4l-Smad2." (PMID 34272474, 2021). "Compared with normal tissues, NEDD4L expression in CRC tissues is decreased significantly, and the expression of NEDD4L results in inhibition of the WNT/β-catenin signaling pathway, without affecting tumor growth." (PMID 36831013, 2023).
cancer (62 papers, 2014 to 2025). A tumor composed of atypical neoplastic, often pleomorphic cells that invade other tissues. "In summary, low NEDD4L expression was closely associated with AML among the 40 types of human cancers." (PMID 34809620, 2021). "There is mounting evidence that demonstrated the association of aberrant NEDD4L expression with diverse human cancers." (PMID 34809620, 2021). "Recently, there is mounting evidence that showed the association of NEDD4L expression with prognosis in diverse human cancers." (PMID 34809620, 2021). "GO and KEGG pathway enrichment analysis revealed that the DEPs were mainly enriched in cell adhesion, cell migration, apoptosis, immune response, cell proliferation, and cell differentiation, indicating that NEDD4L may be involved in many cancer risk pathways." (PMID 39596003, 2024). "Given these major roles of NEDD4L in cell signaling and the cellular DNA damage response, it is not surprising that absence of NEDD4L is associated with disease development, particularly cancer." (PMID 33282879, 2020). "Intriguingly, NEDD4L methylation was negatively correlated with gene expression and could serve as a potential field defect in normal colon mucosa for LS-associated cancer." (PMID 40753397, 2025). "It exerts a tumor suppressive role evidenced by poor prognosis in cancer patients with low NEDD4L expression, such as MM." (PMID 40809696, 2025). "Another member of the NEDD4 family of HECT-type ubiquitin ligases, NEDD4L is involved in the autophagy regulation and mediation of drug sensitivity in diverse cancers." (PMID 40809696, 2025). "Several researchers also suggested that NEDD4L downregulation was strongly correlated with cancer development in various types of solid tumors." (PMID 39717922, 2025). "On the one hand, confirmation that BICC1 and NEDD4L expression is connected to cancer metastasis requires a substantial number of clinical samples." (PMID 39717922, 2025). "NEDD4L is an E3 ubiquitin ligase that has been reported in several studies to inhibit cancer progression by promoting the ubiquitin‐mediated degradation of downstream proteins." (PMID 39717922, 2025). "Studies have demonstrated that NEDD4L functions as an E3 ubiquitin ligase in various cancers by promoting the ubiquitination of target proteins cancer cell proliferation, apoptosis, epithelial-mesenchymal), cancer stem cells, and chemotherapy resistance." (PMID 38302612, 2024). "A series of studies have proved that PI3K/Akt signalling is regulated by NEDD4L in different cancer cells." (PMID 38526036, 2024). "It has been demonstrated that NEDD4 and NEDD4L KO in IECs regulated Lgr5 degradation to mediate Wnt signaling and cancer development in APCmin mice." (PMID 39688910, 2024). "Results of Western blot assay suggested that the expression of NEDD4L in ESCC was apparently lower than that in para-carcinoma tissues." (PMID 38831335, 2024). "In this review, we focus on the structure and function of NEDD4L and the role of NEDD4L in malignant tumors." (PMID 38027016, 2023). "Accumulating investigations have reported different roles of the ubiquitin E3 ligase NEDD4L in cancer biology in various types of malignancies." (PMID 36918822, 2023). "TGF-β-induced SMAD2 phosphorylation was further enhanced in NEDD4L-silenced cancer cells, while NEDD4L overexpression severely impaired the TGFβ-induced phosphorylation of SMAD2." (PMID 37568787, 2023). "Specifically, miR-3679-5p inhibits the transcription of NEDD4L, which mediates the lysosomal degradation of target proteins and is downregulated in various types of cancer to promote cancer progression." (PMID 37981718, 2023). "NEDD4L was previously reported to weaken or promote the progression of various cancers by targeting different substrates." (PMID 37580757, 2023). "ENO1 is a substrate of NEDD4L and is downregulated via ubiquitination to inhibit glycolysis and cancer cell proliferation." (PMID 38027016, 2023).
cancer (continued). "Although NEDD4L has been widely reported to exert cancer-suppressing effects, several studies have elucidated its carcinogenic role." (PMID 38027016, 2023). "Another study showed that miR-93 overexpression in Huh-7 cancer cells facilitated TGF-β-induced EMT by inhibiting NEDD4L expression." (PMID 36293239, 2022). "Phosphatidylinositol‐4, 5‐Bisphosphate 3‐Kinase (PIK3CA) plays a crucial role in PI3K‐related cancer progression, which can be catalyzed through polyubiquitination by NEDD4L, resulting in its proteasome‐dependent degradation." (PMID 36052751, 2022). "We then found out that NEDD4L is downregulated in glioma cancer tissue compared to normal tissue, which is consistent with published data, and the expression level of NEDD4L correlates with prognosis in cancer patients." (PMID 36618071, 2022). "As a member of an E3 ligase NEDD4 family, NEDD4L not only targets membrane proteins including ion channels and transporters, but also triggers the degradation of certain proteins involved in cancer signaling pathways such as Dvl2, SMAD2, and SMAD7." (PMID 36618071, 2022). "Immunohistochemistry (IHC) results indicated that p-mTOR and p-S6K were significantly upregulated in carcinoma tissues, and significantly negatively correlated to NEDD4L." (PMID 35090513, 2022). "It is also critical to design and develop NEDD4L enhancers and inhibitors for cancer treatment in patients with dysregulation of NEDD4L." (PMID 34869021, 2021). "Modulating upstream genes can affect the expression of NEDD4L and thus influence the progression of cancers." (PMID 34869021, 2021). "In this study, we first analyzed the overall expression of NEDD4L in 33 cancer types in TCGA data and found that NEDD4L expression was abnormally changed in a variety of tumors." (PMID 34539897, 2021). "NEDD4L triggers the degradation of certain proteins involved in cancer progression, most of which is due to its E3 ubiquitin ligase function." (PMID 34838005, 2021). "NEDD4L was downregulated in NSCLCs, and this downregulation correlated with lymph node invasion, advanced cancer stage and poor survival." (PMID 34330894, 2021). "NEDD4L is negatively related to interstitial cell infiltration and immune cell infiltration in most common cancers." (PMID 34539897, 2021). "To date, only one HECT E3 ubiquitin ligase specific cancer drug, Bortezomib, has been reported to effectively modulate the activity of the NEDD4L and HERC subfamily ligases discussed in this review." (PMID 33869064, 2021). "Accumulating studies have reported the expression of NEDD4L was regulated by microRNAs during biological process including cancer development." (PMID 34809620, 2021). "It is important to mention that NEDD4L has mutations, copy number variations (CNV) gains, and CNV losses in a variety of human cancers." (PMID 34869021, 2021). "Then, we further explored NEDD4L expression in human cancer samples and normal controls by using the GEPIA databases." (PMID 34809620, 2021). "Among all 33 cancer types in the TCGA database, NEDD4L expression was significantly changed in 17 tumors, accounting for 51.52% of all cancer types." (PMID 34539897, 2021). "As a result, this review presents the structure of NEDD4L and aims to summarize the function of NEDD4L in diverse cancer types." (PMID 34869021, 2021). "In recent years, compelling evidence has shown that NEDD4L accelerates or weakens the progression of various types of cancers by targeting different substrates." (PMID 34869021, 2021). "NEDD4L plays a potential role in the growth of the central nervous system, the regulation of hypertension and the development of cancer and so on." (PMID 34869021, 2021). "For example, ERBB3 (HER3), one of the EGFR family proteins, can undergo NEDD4L-mediated ubiquitination and degradation to down-regulate the signal transduction pathways of occurrence and development in cancers." (PMID 37305161, 2021).
cancer (continued). "We believe that the clinical application of NEDD4L enhancers or inhibitors in cancer therapy will be prospective in the near future." (PMID 34869021, 2021). "It was showed that NEDD4L was the lowest expression level in AML cell lines among 40 types of human cancer cell lines." (PMID 34809620, 2021). "In this study, we aimed to study the expression of NEDD4L in pan-carcinoma and its function in malignant tumors." (PMID 34539897, 2021). "In conclusion, NEDD4L suppresses the carcinogenesis by elevating the degradation of substrates of NEDD4L in most cancer types, while the role of NEDD4L in a few cancer types still remains controversial." (PMID 34869021, 2021). "To date, multiple reports have shown that the expression of NEDD4L in cancers is abnormal, and various proteins have been validated to bind with NEDD4L or be ubiquitinated by NEDD4L, thus modulating the cancer development." (PMID 34869021, 2021). "Among the 33 types of human cancers, significant differences of NEDD4L expression between patients and controls were observed in 10 kinds of human cancers." (PMID 34809620, 2021). "NEDD4L plays a critical role in the regulation of cellular processes of various cancers, most of which is attributed to its E3 ubiquitin ligase function." (PMID 34838005, 2021). "A study demonstrated that the expression of NEDD4L in the cytoplasm of invasive cancer cells is much higher than that in normal or dysplastic epithelial cells." (PMID 34869021, 2021). "By the public data, we identified that low NEDD4L expression was correlated with AML among diverse human cancers." (PMID 34809620, 2021). "NEDD4L level is significantly changed, and it exhibits distinct functions in different carcinomas by regulating certain major pathways (such as TGF-β, WNT and EGFR signaling pathways)." (PMID 37305161, 2021). "Subsequently, two data sets from the GEO database were used for verification, and the results confirmed that NEDD4L was significantly down-regulated in ccRCC carcinoma tissues." (PMID 34458018, 2021). "Based on these unique features of NEDD4L, we were prompted to next investigate the effect of NEDD4L expression on cancer cell proliferation and survival." (PMID 31959741, 2020). "Cancers with low NEDD4L expression tend to display enhanced mitochondrial metabolic functions due to ULK1-mediated autophagy." (PMID 31959741, 2020). "It has been demonstrated that the NEDD4 family plays a vital role in the development and progression of human cancers, and that the expression of NEDD4L is downregulated in various cancer types." (PMID 33748098, 2020). "On the other hand, the role of Neuronal precursor cell developmentally downregulated protein 4 (NEDD4) and its homologue NEDD4L in cancer is controversial." (PMID 31867777, 2020). "NEDD4L also triggers the degradation of certain proteins involved in cancer signaling pathways, including disheveled-2 (Dvl2) and two mothers against decapentaplegic homolog (SMAD) proteins: SMAD2 and SMAD7." (PMID 31959741, 2020). "Multiple cancer cell types have been previously observed to have lowered expression of NEDD4L compared to healthy counterparts." (PMID 31959741, 2020). "Furthermore, in vitro experiments revealed that the effect of NEDD4L knockdown on cancer cell proliferation was reversed by treatment with rapamycin, a selective mTOR inhibitor that suppresses the AKT/mTOR signaling pathway." (PMID 40279519, 2025). "Thus, further studies are warranted to elucidate the precise molecular mechanisms by which NEDD4L influences ferroptosis and its implications for cancer progression." (PMID 39557844, 2024). "Nevertheless, the dual role of NEDD4L in human cancer needs to be further clarified." (PMID 39557844, 2024). "Moreover, we uncovered that NEDD4L depletion inhibited ferroptosis and promoted cell proliferation, which subsequently promoted cancer progression in vivo and in vitro." (PMID 39557844, 2024).
cancer (continued). "Further study is essential and worthwhile to clarify whether NEDD4L can be applied in clinical trials for cancer therapy." (PMID 39557844, 2024). "In this section, we have summarized how NEDD4L regulates multiple stages of cancer." (PMID 37568787, 2023). "NEDD4L plays a crucial role in drug sensitivity during cancer therapy." (PMID 38027016, 2023). "Levels of c-Myc were found to be suppressed in NEDD4L-overexpressing A549 cancer cells." (PMID 37568787, 2023). "Upstream regulators modulate NEDD4L and its impact on cancers." (PMID 38027016, 2023). "As a member of an E3-ubiquitin protein ligase NEDD4 family, NEDD4L is expressed in various types of cancer cells and may have carcinogenic properties." (PMID 36618071, 2022). "NEDD4L serves as a tumor‐suppressor gene in a variety of cancer." (PMID 36052751, 2022). "Upstream gene modulates NEDD4L gene and its impact on cancers." (PMID 34869021, 2021). "Developing clinical drugs targeting NEDD4L could be a potential therapeutic strategy for cancer therapy in the future." (PMID 34869021, 2021). "The expression level of NEDD4L has also changed significantly in human cancers." (PMID 34539897, 2021). "In some specific malignant tumors, the design of the NEDD4L enhancer may contribute to the better treatment of cancer patients, but the targeted inhibition of NEDD4L probably controls the procedure of some other cancer types." (PMID 34869021, 2021). "NEDD4L gene modulates downstream genes and its impact on cancers." (PMID 34869021, 2021). "The expression level of NEDD4L, an E3 ubiquitin ligase, has changed significantly in human cancers." (PMID 34539897, 2021). "Taken together, NEDD4L expression is abnormal in most common cancers." (PMID 34539897, 2021). "Our study provides novel insights into the role of NEDD4L in pan-cancer." (PMID 34539897, 2021). "To investigate NEDD4L expression pattern in human cancers, we first used the CCLE databases." (PMID 34809620, 2021). "Also, NEDD4L has been shown to be involved in the regulation of certain major signaling pathways in carcinoma, including the WNT, and TGF-β signaling pathways (Zou, Levy-Cohen & Blank, 2015)." (PMID 34458018, 2021). "It is reported that NEDD4L acts a pivotal part in the prognosis of various malignant carcinomas." (PMID 34458018, 2021). "Therefore, the increased mitochondrial energy production found in NEDD4L-depleted cancers can be effectively targeted by autophagy inhibition, which can be considered as a promising therapeutic approach." (PMID 31959741, 2020). "The role of NEDD4 and NEDD4L in cancer progression has been controversial." (PMID 31867777, 2020). "Therefore, ubiquitin ligase-mediated autophagy plays a critical role in regulating mitochondrial metabolism, thereby contributing to the growth and survival of certain cancers with low NEDD4L levels." (PMID 31959741, 2020). "We could therefore conclude that NEDD4L depletion in cancer cells facilitated ULK1-mediated autophagy and ASCT2-mediated glutamine uptake to supply appropriate fuel to activate mitochondrial metabolism and maintain mitochondrial functional integrity." (PMID 31959741, 2020). "Moreover, the growth rate of shNEDD4L cells was significantly suppressed by the ectopic expression of NEDD4L, suggesting that NEDD4L negatively regulates cancer cell proliferation." (PMID 31959741, 2020). "Low-NEDD4L expression improved cancer cell growth and viability." (PMID 31959741, 2020). "Overall, therapeutic strategies targeting NEDD4L to treat cancer may be feasible." (PMID 38027016, 2023). "However, NEDD4L was confirmed to have distinct functions in different carcinomas." (PMID 34458018, 2021).